SLC66A3 (solute carrier family 66 member 3)
Synonyms: C2orf22; PQLC3; MGC33602
Tractability: Antibody: UniProt predicts a signal peptide or a membrane-spanning region.
Gene: Protein-coding gene on chromosome 2 (11,155,198 to 11,178,870, forward strand). Ensembl gene ENSG00000162976.
Subcellular location: Membrane
Subcellular location (Human Protein Atlas): Cytosol
Gene Ontology:
Cellular component: membrane
Genetic constraint (gnomAD): Loss-of-function variants: 15 observed, 14.32 expected, observed/expected ratio (o/e) 1.05, 90% interval 0.7 to 1.6. The upper end of that interval is the gene's LOEUF score, 1.6, which puts it in group 6 of 6, group 1 being the genes least tolerant of losing a copy. Missense variants: 185 observed, 158.34 expected, observed/expected ratio (o/e) 1.17, 90% interval 1.04 to 1.32. Synonymous variants: 84 observed, 71.62 expected, observed/expected ratio (o/e) 1.17, 90% interval 0.98 to 1.41.
Homologues: Orthologues: chimpanzee SLC66A3 (99% identical), macaque SLC66A3 (99% identical), mouse Slc66a3 (85% identical), rat Slc66a3 (85% identical), pig SLC66A3 (79% identical), guinea pig SLC66A3 (76% identical), rabbit SLC66A3 (74% identical), dog SLC66A3 (61% identical), tropical clawed frog slc66a3 (61% identical), zebrafish slc66a3 (58% identical), Drosophila melanogaster CG1265 (34% identical). Paralogues in human: MPDU1 (27% identical).
Diseases named in the same sentence as SLC66A3 in open-access papers:
SLC66A3 is named in the same sentence as 4 diseases in open-access papers, as found by Europe PMC text mining. Sharing a sentence is not in itself a finding about the gene and the disease. The quoted sentences say what the papers report.
tumor (2 papers, 2025). "We analyzed the expressions of SLC39A1, SLC50A1 and SLC66A3 across tumour stages from Stage I to Stage IV in the TCGA database." (PMID 40462487, 2025).
SLC66A3 also shares sentences with these, for which no sentence is quoted: acute myocardial infarction (1 paper); cardiac hypertrophy (1); Hyperglycemia (1).